EGFR (epidermal growth factor receptor)
Diseases named in the same sentence as EGFR in open-access papers (continued):
Sharing a sentence is not in itself a finding about the gene and the disease.
lung cancer (continued). "All patients with EGFR-mutant lung cancers eventually develop acquired resistance to EGFR TKIs." (PMID 25699082, 2015). "Activating EGFR mutations are detected in substantial numbers of lung cancer patients and are more commonly observed in women and non-smokers." (PMID 26134262, 2015). "The same phenotypic changes could be induced by selecting for resistance to docetaxel in the sensitive prostate cancer cell line DU145 and to the EGFR inhibitor Tarceva in the sensitive lung cancer line H358 (Fig1A)." (PMID 25872941, 2015). "We also analyzed the expression of EGFRtyr1068 and EGFRtyr1173 in a series of 91 lung cancer specimens, with (n=39) or without (n=52) EGFR-sensitizing mutations." (PMID 26247735, 2015). "Originally, Iressa, a selective EGFR inhibitor, showed promising results among Asian patients, but not in Western populations, suggesting a possible role of ethnic differences between Asian and Western lung cancer patients." (PMID 26047809, 2015). "Interestingly, many studies relating to TKI-resistance focus on lung cancer models, and particularly on resistance to the EGFR-specific TKI called gefitinib." (PMID 26287249, 2015). "However, afatinib and 3rd generation EGFR-TKIs, osimertinib and rociletinib, effectively inhibited the proliferation of lung cancer cells." (PMID 26515464, 2015). "Higher level of interleukin-6 (IL-6) existed in lung cancer patients and mutant EGFR and TGFβ signal requires the upregulation of IL-6 through the gp130/JAK pathway to overactive STAT3, an oncogenic protein which has been considered as a potential target for cancer therapy." (PMID 26166037, 2015). "The number of samples was 11 of EGFR mutation-positive lung cancer, 19 of EGFR mutation-negative lung cancer, 11 of leucocyte DNA from normal individuals and 7 of cfDNA from normal individuals." (PMID 26126624, 2015). "Interestingly, an inverse correlation of miR-542-5p transcript and EGFR protein levels was found in human lung cancer tissues." (PMID 26273639, 2015). "Recently, increasing numbers of miRNAs are correlated with the drug resistance of lung cancer cells to anti-EGFR agents, indicating that miRNAs may serve as novel targets and/or promising predictive biomarkers for anti-EGFR therapy." (PMID 26273639, 2015). "In the present study, we sought to determine whether the lncRNA UCA1 can induce acquired resistance to EGFR-TKIs via cell apoptosis and activation of the PI3K/AKT/mTOR pathway in EGFR-mutant lung cancer." (PMID 26160838, 2015). "EGFR inhibitors comprise a novel, molecule-targeting treatment for lung cancer." (PMID 25452785, 2015). "Therefore, it is of great significance to develop new small molecules targeting EGFR that can overcome the chemotherapy resistance to combat lung cancer, especially the NSCLC." (PMID 25730907, 2015). "Furthermore, deletion of Cebpb had no impact on lung tumor burden in a lung specific, conditional mutant EGFR lung cancer mouse model." (PMID 25767874, 2015). "In addition to the IPASS findings, there have been six randomized controlled phase III trials comparing EGFR TKIs (gefitinib, erlotinib or afatinib) to chemotherapy in EGFR-mutant lung cancer patients, both in Asian and Caucasian populations." (PMID 25810955, 2015). "For example, a critical role for tankyrase and Wnt/β-catenin signaling was identified for maintenance of lung cancer cells during EGFR inhibition and subsequent inhibition of tankyrase significantly enhanced the antitumor activity of EGFR inhibitors in NSCLC cells." (PMID 26513298, 2015). "Amongst the currently accessible drugs against lung cancer, gefitinib (Iressa) and erlotinib (Tarceva), so called EGF receptor tyrosine kinase inhibitors (EGFR-TKIs), are effective in patients with EGFR mutations, including exon 19 deletion and exon 21 substitution (L858R)." (PMID 26312766, 2015).
lung cancer (continued). "Also, 1, 25-dihydroxyvitamin D suppresses epidermal growth factor receptor, which signals several tumorigenic processes, such as proliferation and metastasis, in lung cancer." (PMID 26704811, 2015). "Correlation of EGFRtyr1068 expression and EGFR inhibitor sensitivity was also found in commercial lung cancer cell lines, where EGFRtyr1068 was strictly associated with sensitivity regardless of EGFR mutational status." (PMID 26247735, 2015). "In EGFR wild-type lung cancer, immune evasion induced by PD-L1 played an important role." (PMID 25895031, 2015). "Thus, EGFR mutant lung cancers that transform to SCLC invariably lose RB expression, similar to classical SCLC." (PMID 25758528, 2015). "Recent data suggest that HDACis can increase sensitivity to EGFR-TKIs in lung cancer cells." (PMID 25552401, 2015). "Lung cancers in never-smokers are more frequently associated with adenocarcinoma with EGFR mutations and less frequently with KRAS mutations." (PMID 25760072, 2015). "We found that this compound could suppress gefitinib-sensitive and -resistant lung cancer cell growth by inhibiting EGFR activity and its downstream signaling pathways in vitro and ex vivo." (PMID 26517520, 2015). "In PC9 mutant, EGFR-addicted lung cancer cells, EGFR inhibitiontriggers apoptosis in the vast majority of cells in vitro, uncovering approximately 0.3%that are drug tolerant, quiescent, and expressing the stem cell marker CD133 and thehistone H3K4 demethylase KDM5A." (PMID 25686219, 2015). "However, to the best of our knowledge, there is no clinical trial specifically investigating the efficacy of EGFR TKIs in lung cancer patients who have recurrent disease after surgical resection." (PMID 26486077, 2015). "In recent phase III trials of the EGFR-TKI, gefitinib, demonstrated a significant superiority on progression-free survival (PFS) over standard chemotherapies as the first-line treatment for EGFR-mutated advanced non–small cell lung cancer (NSCLC)." (PMID 25886066, 2015). "However, it is possible that the β-catenin pathway is more highly activated in lung cancer tissues derived from patients who are resistant to EGFR-TKI treatment than in tissues derived from patients in whom the EGFR-TKI treatment is effective." (PMID 26268703, 2015). "EGFR mutations and the EML4-ALK translocation are defined as driver mutations because these alterations are responsible for both initiation and maintenance of lung cancer." (PMID 25760072, 2015). "However, the clinical benefits of these anti-EGFR agents are often limited, mainly due to the heterogeneity of lung cancer and the drug resistance to anti-EGFR therapy." (PMID 26273639, 2015). "STAT3-mediated Akt activation resulted EGFR-TKI resistance in lung cancer cells." (PMID 25869210, 2015). "Our findings provide new insights into the molecular mechanisms of TUSC2-mediated tumor suppression, and suggest that the therapeutic activity of TUSC2 could extend the use of erlotinib to lung cancer patients with wildtype EGFR." (PMID 26053020, 2015). "However, clinical studies have shown that a small population of patients with amplified, wild-type EGFR lung cancers also benefit from gefitinib or erlotinib." (PMID 26220863, 2015). "EGFR and KRAS somatic mutations, previously detected by SS, were confirmed by both pipelines either in SF and matched FFPE, validating the high specificity of the Ion AmpliSeq Colon and Lung Cancer panel for the identification of these mutations." (PMID 26633390, 2015). "However, despite initial dramatic responses to gefitinib and erlotinib in patients with EGFR-mutant lung cancers, acquired resistance inevitably occurs at a median of 10–13 months after treatment initiation." (PMID 26134262, 2015). "The therapeutic activity of TUSC2 could extend the use of erlotinib to lung cancer patients with wildtype EGFR." (PMID 26053020, 2015).
lung cancer (continued). "MMP-7 overexpression could also regulate the proliferation of lung cancers through activation of EGFR and the production of mature HB-EGF to activate the receptor ErbB4." (PMID 25588786, 2015). "Particularly, the application of miRNAs as predictive biomarkers may also be beneficial for predicting therapeutic response to anti-EGFR agents in advanced lung cancer patients and lead to a higher level of personalized therapy." (PMID 26273639, 2015). "The treatment of lung cancer could lead to an acquired resistance to EGFR tyrosine kinase inhibitors (TKIs)." (PMID 26516313, 2015). "Compared to lung cancers with EGFR activating mutations, tumours with no mutation detected in EGFR are less sensitive to the EGFR TKIs, erlotinib and gefitinib." (PMID 26101870, 2015). "Therefore, overcoming the primary or secondary resistance to EGFR-TKIs remains one of the most significant challenges for the successful treatment of lung cancer." (PMID 25925741, 2015). "Thus, protocols testing such intermittent high dose pulses of erlotinib specifically in patients with EGFR-mutant lung cancer warrant clinical exploration." (PMID 26540572, 2015). "They described that the highest incidence of VTE is within 1 month after lung cancer surgery and high risk factors for VTE include incomplete surgical resection, postoperative use of anti-angiogenesis drugs, EGFR-TKI application and an increase in preoperative D-dimer level." (PMID 26380084, 2015). "In conclusion, the present study describes a case in which favorable results and a good recovery were achieved based on the selection of surgical treatment combined with radiation and EGFR inhibitor therapy, an option that is recommended for patients with lung cancer metastasized to the spine." (PMID 25452785, 2015). "Dysregulation of the EGFR signaling is frequently found in lung cancer." (PMID 26273639, 2015). "EGFR can promote the metastasis of tumor cells partially by regulating integrin expression and functional subunit recombination, and it is invasion and metastasis that mainly result in the failure of lung cancer treatment and final death." (PMID 26648997, 2015). "We conclude that EGFRtyr1068 may represent a potential candidate biomarker predicting erlotinib response at CSC-level in EGFR-WT lung cancer patients." (PMID 26247735, 2015). "We hypothesized that TUSC2 systemic delivery to wild type EGFR lung cancer cells would complement therapeutic benefits of existing small molecule drugs." (PMID 26053020, 2015). "On the other hand, in line with the data underscoring the relevance of non-coding RNAs in the pathogenesis of lung cancer and modulation of response to systemic therapies, microRNAs (miRNAs) have been supposed to play an important role in resistance to EGFR-TKIs." (PMID 26435742, 2015). "In addition to EGFR mutations, MET amplification/over-expression was also reported as another common EGFR TKI resistance mechanism in lung cancer." (PMID 25674538, 2015). "Taken together, these findings suggest that upstream inhibition of the EGFR/HER receptors may be effective in treating a subset of KRAS mutant lung cancers." (PMID 25992771, 2015). "Further, treatment of lung cancer cells with EGFR specific small molecule inhibitor gefitinib (Iressa), strongly inhibited the DSB repair after ionizing radiation, indicating that EGFR promotes radiation response by augmenting DNA repair capacity of cancer cells." (PMID 26546517, 2015). "We propose that the EGFR dephosphorylation induced by VNR is related to cell growth inhibitory activity of VNR, and that this is one of the mechanisms of the synergistic effect of VNR + 5-FU in EGFR-mutated lung cancer cells." (PMID 25573239, 2015). "We proposed the hypothesis that ER could induce resistance to EGFR-TKIs in lung cancer and that addition of an ER antagonist could reverse the resistance." (PMID 26096604, 2015).
lung cancer (continued). "However, the development of resistance, despite good initial responses, in patients with EGFR-mutant lung cancer is inevitable." (PMID 25780909, 2015). "Currently, epidermal growth factor receptor (EGFR) tyrosine kinase inhibitors (TKIs), including gefitinib, erlotinib and afatinib, are highly effective in treating lung cancer patients with specific EGFR mutations in their tumor samples, such as exon 19 deletion or exon 21 L858R mutation." (PMID 25807554, 2015). "To determine whether EGFR expression is commonly lost in EGFR mutant lung cancers that transform to SCLC, we performed IHC analysis on seven resistant cases of EGFR mutant cancers that had transformed to SCLC along with ten cases that retained NSCLC histology." (PMID 25758528, 2015). "Serglycin core protein was detected only in the culture medium of aggressive cell lines such as A549, NCI-H23, and HCC827 lung cancer cells and DLD-1 colon cancer cells as well as MDA-MB-231 breast cancer cells as previously shown, which harbor KRAS or HER1/EGFR mutations." (PMID 26581653, 2015). "Currently, a number of miRNAs has been described which may have a specific role in lung cancer pathogenesis, biological and clinical disease behaviour as well as in modulating response to anticancer treatments, particularly EGFR-TKIs." (PMID 26435742, 2015). "Considering that we have provided pharmacologic evidence for uncharacterized CTED mutants as well, we think even larger proportion of patients with GBM or lung cancer may benefit from EGFR targeted therapies than what is predicted." (PMID 25826094, 2015). "Regardless, studies suggest that c-Met may be an effective therapeutic target to overcome resistance to EGFR inhibitors in lung cancer." (PMID 26000702, 2015). "For examples, miR-542-5p could downregulate EGFR mRNA and protein expression in human lung cancer H3255, A549, and HCC827 cells and inhibit the growth of these cancer cells." (PMID 26273639, 2015). "This is similar to the common Asian population, which suggests that EGFR mutations are not responsible for the increased incidence of MPM patients involving lung cancer." (PMID 26466785, 2015). "According to our findings, cigarette smoking could possibly induce IL-1β in lung carcinoma and transactivate EGFR through CXCL1-CXCR2 axis." (PMID 26462152, 2015). "Although many molecular genetic studies have implicated certain genetic mutations in non-small cell lung cancer (NSCLC), including mutations in the EGFR, PIK3CA, BRAF, KRAS, and ALK genes, only a few studies have focused on the genetic events associated with salivary gland-type lung carcinomas." (PMID 26373952, 2015). "Therefore, our findings indicate that Rab25 plays a crucial role in EGFR signaling in lung cancer with wtEGFR." (PMID 24658031, 2014). "Interestingly, we found that EGF-induced EGFR endocytosis is existed differently between gefitinib-sensitive and -insensitive lung cancer cell lines." (PMID 24658031, 2014). "E-cadherin overexpression could induce apoptosis, increases sensitivity to epidermal growth factor receptor inhibitors in lung cancer cell lines." (PMID 25010679, 2014). "In lung cancer, MET mutations are rare, but amplification is seen in up to 21%, resulting in constitutive MET activation and is believed to be a potential mechanism of acquired EGFR TKI resistance." (PMID 25505733, 2014). "Contrary to our results, EGFR TKI was reported to decrease PGE2 production from lung cancer cells." (PMID 25240937, 2014). "We also demonstrated that suppressing EGFR endocytosis could aeffect cell viability and the gefitinib response in gefitinib-insensitive lung cancer with wtEGFR." (PMID 24658031, 2014). "Metastatic lung cancer patients with EGFR mutations have a better prognosis as compared to EGFR mutation negative patients." (PMID 25548673, 2014). "EGFR kinase domain mutations are prevalent in lung cancers in non-smokers and have been established as valid predictors of increased sensitivity to EGFR kinase inhibitors." (PMID 25028095, 2014).
lung cancer (continued). "In conclusion, we provided novel insights that EGFR endocytosis is important for treating lung cancer with wtEGFR in in vitro and in vivo models, suggesting that it is a promising target to improve therapeutic efficacy when its inhibitor and EGFR-TKI are administered together." (PMID 24658031, 2014). "On the basis of this study, in May 2013 the U.S Food and Drug Administration (FDA) approved erlotinib for use in patients with lung cancers harboring EGFR exon 19 deletions and EGFR L858R substitutions." (PMID 25364578, 2014). "Mutant forms of EGFR are associated with cancer development, including lung cancer in non-smokers, and with elevated sensitivity to EGFR inhibitors, such as erlotinib and gefitinib." (PMID 25594057, 2014). "Therefore, in this study, we investigated the potential molecular mechanism that contributes to cell viability and the response of gefitinib, one of the EGFR-TKIs, in lung cancer models with wide-type EGFR (wtEGFR)." (PMID 24658031, 2014). "Recognizing that the diffusion of diagnostic tests is a conditio sine qua non for the success of personalized lung cancer therapies, this study analyzed the diffusion of epidermal growth factor receptor (EGFR) and anaplastic lymphoma kinase (ALK) tests in Germany." (PMID 25562146, 2014). "Therefore it was suggested that chemotherapy-induced up-regulation of pEGFR and pERK reinforced the sensitivity of lung cancer cells to subsequently used EGFR-TKI, and finally resulted in improved outcomes." (PMID 25474307, 2014). "In addition, we identified that EGFR endocytosis-related Rab25 expression is crucially considered when patients with lung cancer and wtEGFR are treated with gefitinib." (PMID 24658031, 2014). "Lung cancer cells express ErbB receptors and anti-epidermal growth factor receptor (EGFR) monoclonal antibodies (Mab) such as Cetuximab, Panitumumab and Necitumumab have been widely used in clinical trials by intravenous administration, showing limited efficacy and poor tolerability." (PMID 25238453, 2014). "Lung cancer is the major cause of cancer-related deaths and many cases of Non Small Cell Lung Cancer (NSCLC), a common type of lung cancer, have frequent genetic/oncogenic activation of EGFR, KRAS, PIK3CA, BRAF, and others that drive tumor growth." (PMID 25466244, 2014). "Thus, targeting EGFR by RTK inhibitors will restore the tumor suppressor functions of GPRC5A in lung cancer cells." (PMID 25311788, 2014). "EGFR is overexpressed in a number of cancers, including breast and lung cancer." (PMID 24992720, 2014). "In this study, we examined the phenotypic and molecular differences between gefitinib -sensitive and -insensitive lung cancer cells with wtEGFR using in vitro and in vivo models and found a potential relationship between gefitinib response and EGFR endocytosis." (PMID 24658031, 2014). "In contrast however, a positive association between EGFR mutation and age was reported among never-smoker lung cancer patients." (PMID 25348872, 2014). "Although the EGF receptor tyrosine kinase inhibitors (EGFR-TKI) gefitinib have shown dramatic effects against EGFR mutant lung cancer, patients become resistant by various mechanisms, including gatekeeper EGFR-T790M mutation, MET amplification, and KRAS mutation, thereafter relapsing." (PMID 24939055, 2014). "Similarly, EGFR-mutant lung cancer cells treated with an EGFR inhibitor downregulate PTEN and increase AKT survival signaling." (PMID 25500581, 2014). "But the clinical efficacy of those anti-EGFR targeted drug in lung cancer is inconsistent." (PMID 24625581, 2014). "Nevertheless, we suggested that CX-4945 could be useful for treatment of EGFR-mutant lung cancer with T790M-mediated resistance." (PMID 25486409, 2014). "In conclusion, dual-agent molecular targeting through T-DM1 may be a promising therapy in HER-2 positive lung cancer even in tumors which had developed resistance to EGFR-TKIs." (PMID 24898067, 2014).